MIF (macrophage migration inhibitory factor)
Diseases named in the same sentence as MIF in open-access papers (continued):
Sharing a sentence is not in itself a finding about the gene and the disease.
pulmonary hypertension (continued). "Treatment with the MIF antagonist ISO-1 or anti-CD74 neutralizing antibodies reduced inflammatory cell infiltration and, in addition, reversed the development of pulmonary hypertension in rats." (PMID 36553040, 2022). "MIF has been found to be related to proliferation of SMCs, and a study on rats under hypobaric hypoxia showed that an increase in MIF induces proliferation of PASMCs through activation of ERK1/2 and JNK proteins, contributing to the pulmonary hypertension." (PMID 34434114, 2021). "Furthermore, in a mouse model of hypoxia-induced pulmonary hypertension, the pulmonary vascular remodeling, increased right ventricular systolic pressures and right sided cardiac hypertrophy were all significantly decreased in the presence of a small molecule inhibitor of MIF." (PMID 30083544, 2018).
heart failure (18 papers, 2013 to 2025). Inability of the heart to pump blood at an adequate rate to meet tissue metabolic requirements. "Many of the involved inflammatory markers, such as IL-6, CRP, TNF-α, IL-1β, and macrophage inhibitory factor (MIF), have been associated with post-MI hypertrophy, remodeling, persistent systolic dysfunction, heart failure, and mortality." (PMID 38558749, 2024). "Elevated expression of MIF has been reported to be associated with all‐cause mortality in patients with heart failure." (PMID 38924383, 2024). "In our cohort, we demonstrate a clear association of MIF with symptoms, right heart loading conditions, and long-term outcome of these patients that was comparable with established biomarkers in heart failure." (PMID 29728137, 2018). "For example, D-DT is promising therapeutic target candidate in heart failure and the role of MIF is only small." (PMID 35091838, 2022). "These first data on MIF in HFpEF should stimulate further research to elucidate the role of this cytokine in heart failure." (PMID 29728137, 2018). "Our study gives new insight into the role of MIF in heart failure and thereby complements prior studies to elucidate the “MIF story” in heart failure." (PMID 29027966, 2017). "Effect of MIF signaling in inflammatory cardiomyopathy, cardiac remodeling, and heart failure." (PMID 40092999, 2025). "Investigators found significantly higher stem cell growth factor beta (SCGF beta), hepatocyte growth factor (HGF), monokine induced by interferon gamma (CXCL9), and macrophage inhibitory factor (MIF) in Chagas myocardiopathy patients with advanced heart failure compared to the control group." (PMID 38133693, 2023). "The expression of MIF and GRK2 was significantly upregulated in H9C2 cardiomyocytes as a function of glucose concentration, and GRK2-mediated increases in MIF levels were linked to cardiac insufficiency in diabetic patients." (PMID 36871006, 2023). "Despite these study limitations, our results provide important new aspects on MIF in heart failure." (PMID 29027966, 2017). "As an upregulation of GRK2 in cardiomyocytes precedes the development of heart failure, this finding might suggest that MIF could promote heart failure by amplifying GRK2 expression." (PMID 26347749, 2015). "Based on a comprehensive interpretation of these findings, we hypothesized that a molecule that has anti-oxidative and anti-inflammatory effects and also has the ability to control MIF would be a promising novel therapeutic agent for the treatment of heart failure." (PMID 35335938, 2022). "Experimental animal models and clinical data implicate MIF in the development and progression of ICM, cardiac remodeling, and heart failure." (PMID 40092999, 2025). "We therefore investigated MIF and HIF-1α expression in myocardial samples from patients with heart failure and show different expression levels depending on the underlying type of cardiomyopathy." (PMID 29027966, 2017). "Clinical studies found a high MIF level in patients with ACS and heart failure." (PMID 35046995, 2021). "Myocardial biopsy of the heart of patients with nonischemic heart failure revealed that myocardial MIF content was positively correlated with the degree of cardiac fibrosis and was an independent risk factor for adverse cardiovascular events." (PMID 30983881, 2019). "Third, our data are just descriptive and do neither give a mechanistical insight into the role of the HIF-1α/MIF axis in heart failure nor provide data on outcome and prognosis." (PMID 29027966, 2017). "To date, no studies exist that report on the HIF-1α/MIF axis in heart failure." (PMID 29027966, 2017).
type 1 diabetes (18 papers, 2010 to 2025). "For prediction of death, the statistical variable selection procedure resulted in a model containing the variables EuroSCORE, insulin-dependent diabetes, and the MIF CATT7 allele." (PMID 32932965, 2020). "Interestingly, our EC model showed an increase in CXCL10, ICAM1, IL-6, and MIF, which are associated with type I diabetes development." (PMID 31835296, 2019). "In other cardiac diseased models, such as pressure overload-induced cardiac hypertrophy, diabetic cardiomyopathy induced by type 1 diabetes and doxorubicin-induced cardiomyopathy, MIF deficiency exacerbated the impaired cardiac function and lead to increased mortality." (PMID 30678084, 2019). "The MIF/CD74 signaling pathway promotes macrophage-mediated inflammation in type 1 diabetes, and MIF controls the recruitment of inflammatory cells via chemokine receptors CXCR2 and CXCR4." (PMID 34445689, 2021). "Recently, it was demonstrated that the MIF/CD74 signaling pathway promotes macrophage-mediated inflammation in type 1 diabetes." (PMID 31866994, 2019). "These included IL-6 signaling, IL-10 signaling, TREM1 signaling, MIF regulation of innate immunity, type I diabetes mellitus signaling, p38 MAPK signaling, toll-like receptor signaling, and acute phase response signaling." (PMID 21777429, 2011). "The pathways related to the Th1 response (HMGB1 Signaling, Neuroinflammation Signaling pathway, TREM1 Signaling, MIF-mediated Glucocorticoid Regulation, Dendritic Cell Maturation, and Type I Diabetes Mellitus Signaling) were activated at 6, 12 and 24 h after M. avium infection." (PMID 33520738, 2020). "However, some evidence has suggested cardioprotective roles of MIF under various pathological conditions, including type 1 diabetes and ischemia-reperfusion." (PMID 26359352, 2015). "Recently, it was demonstrated that small molecule inhibitors of MIF, inhibit cancer development in animal models, reduce the severity of experimental autoimmune encephalomyelitis and lower blood glucose in an animal model of non-insulin-dependent diabetes mellitus." (PMID 31866994, 2019). "Additionally, the most significant canonical pathways were IL-6 signaling, IL-10 signaling, TREM1 signaling, MIF regulation of innate immunity, type I diabetes mellitus signaling, p38 MAPK signaling, toll-like receptor signaling, and acute phase response signaling." (PMID 21777429, 2011).
cervical cancer (17 papers, 2014 to 2024). A primary or metastatic malignant neoplasm involving the cervix. "Moreover, the genetic polymorphism MIF-173 was associated with a higher risk of early cervical cancer and lymph node metastasis and also with the risk of gastrointestinal cancer and hematological malignancy." (PMID 32155795, 2020). "Patients with the CC genotype exhibited higher MIF serum concentration, which could increase the risk of early stage cervical cancer and lymphatic metastasis." (PMID 31284453, 2019). "The genetic polymorphism MIF-173 is associated with cervical cancer in humans." (PMID 31284453, 2019). "The staining of TGFβ, PD-L1, IL-10, FOXP3, IL-17, and MIF was cytoplasmic and present in 25%, 9.4%, 56.2%, 7.2%, 76.3%, 86.1%, and 85.2%, respectively, of the cervical cancer cases." (PMID 39061137, 2024). "Immunohistochemical studies demonstrated overexpression of MIF in cervical cancer tissues compared to healthy cervix and dysplasia." (PMID 35196323, 2022). "D-dopachrome tautomerase (D-DT), a homolog of macrophage migration inhibitory factor (MIF), can promote the invasion of cervical cancer cells when it is overexpressed." (PMID 33671013, 2021). "Previous studies found that DDT and MIF are involved in proliferation, migration, and invasion of cervical cancer." (PMID 32719721, 2020). "Macrophage migration inhibitory factor (MIF) expression was significantly increased in cervical cancer samples." (PMID 31284453, 2019). "SiHa and CaSki cervical cancer cells were discovered to secret soluble MIF into cell culture supernatants." (PMID 31284453, 2019). "Interestingly, our results showed a strong association correlation between CD163 + CD204 + M2TAM, via STAT3/NF-κB pathways and the expression of CD25, FOXP3, MIF, and IL-17 in 56.2%, 76.3%, 85.2%, and 86.1%, respectively, of 691 patients with cervical cancer." (PMID 39061137, 2024). "In cervical cancer, CAFs and B cells communicate through MIF-(CD74+CXCR4) and MIF-(CD74+CD44)." (PMID 38157264, 2023). "Previously, we identified cervicovaginal MIF as a potential biomarker for cervical cancer." (PMID 35196323, 2022). "Similarly, MIF promotes cervical cancer (CeCa) cell proliferation through increasing cyclin D, p16 and c-Myc and decreasing cyclin E expression in tumor cells and upregulates Src and FAK expression to promote tumor cell migration." (PMID 35842634, 2022). "Overexpression of MIF in SCC and its precancerous lesions (CIN1-3) and in SiHa and C-33A indicates that MIF may play an important role in the pathogenesis of cervical cancer." (PMID 28250389, 2014). "MIF protein and mRNA expression was analyzed by Western blotting, ELISA and RT-PCR in uterine cervical cancer cell lines SiHa and CaSki and their supernatant, and on 80 biopsies (cervical dysplasias,in situ carcinomas and invasive carcinomas) of uterine cervical tissue." (PMID 28250389, 2014).
cyst (17 papers, 2015 to 2026). A sac-like closed membranous structure that may be empty or contain fluid or amorphous material. "In PC1-deficient murine kidneys, MIF was up-regulated in CLECs and accumulated in the cyst fluid of human ADPKD kidneys." (PMID 41431718, 2026). "However, the underlying mechanisms leading to induction of MIF in cyst-lining cells remained elusive." (PMID 32885302, 2020). "In addition, MIF was upregulated in cyst-lining epithelial kidney cells of Pkd1-deficient mice as well as in the cyst fluid of human ADPKD kidneys." (PMID 31514750, 2019). "In PKD mice, MIF is essential for the recruitment and retention of renal macrophages, which further promote cyst growth and inflammation." (PMID 41431718, 2026). "Both genetic deletion and pharmacologic inhibition of MIF delayed cyst growth in various murine ADPKD models." (PMID 41431718, 2026). "The macrophage migration inhibitory factor (MIF) is upregulated in cyst-lying cells, and it is mediated by hypoxia-inducible transcription factor (HIF) 1α and cAMP." (PMID 37241147, 2023). "Macrophage migration inhibitory factor (MIF) reported to be upregulated in cyst-lining epithelial cells of Pkd1 mutant mouse kidneys, accumulates in cyst fluid of human ADPKD kidneys." (PMID 35847973, 2022). "Treatment with ISO-1, a MIF inhibitor, efficiently slowed cyst growth, accompanied with an increase in apoptosis." (PMID 35847973, 2022). "The conclusion from this analysis is supported by our recent study, which found that MIF played an important role in regulating different signaling pathways, and the inhibition of MIF delays cyst growth in Pkd1 mutant mice." (PMID 36611841, 2022). "Second, we found that the progression of PKD can be influenced by the presence of inflammatory factors such as tumor necrosis factor alpha (TNF-α) and macrophage migration inhibitory factor (MIF) in the cyst fluid." (PMID 35847973, 2022). "In patients with ADPKD, the inflammatory markers MCP-1 and macrophage migration inhibitory factor (MIF) are elevated in the urine and cyst fluid." (PMID 36106024, 2022). "HIF-1α and cAMP can induce the expression of MIF by primary tubular cells and cyst-lining epithelial cells and promotes cyst cell proliferation independently of macrophages." (PMID 35563296, 2022). "Next to HIF-1α, we also found cAMP which is a main driver of cyst growth in ADPKD as an additional regulator of MIF expression." (PMID 32885302, 2020). "Nevertheless, our data from the in vitro cyst model suggest that MIF mediates cyst growth not only by recruitment of macrophages but also in a direct manner." (PMID 32885302, 2020). "Macrophage migration inhibitory factor (MIF) was found to be upregulated in cyst-lining cells in a mouse model of polycystic kidney disease and to promote cyst growth." (PMID 32885302, 2020). "Next to HIF-1α and hypoxia, we found MIF being additionally regulated by cAMP which is a strong promotor of cyst growth." (PMID 32885302, 2020). "Pharmacological stabilization of HIF-1α resulted in significant increase of MIF in cyst epithelial cells whereas tubule-specific knockout of HIF-1α prevented MIF upregulation." (PMID 32885302, 2020). "Recently, it has been shown that upregulation of MIF in cyst epithelial cells of an ADPKD mouse model resulted in increased cyst growth." (PMID 32885302, 2020). "Since MIF promoted plMDCK cell proliferation in vitro, we next tested for proliferation markers in our plMDCK cyst model." (PMID 32885302, 2020). "MIF expression did not only increase in overall levels but also showed different subcellular patterns which correlated with the degree of cyst formation and expansion." (PMID 32885302, 2020). "This is further supported by our findings showing coexpression of MIF and ABCA1 in cyst-lining cells and correlating numbers of MIF- and ABCA1-positive cysts in kidneys with different genetic backgrounds and upon treatment with ICA." (PMID 32885302, 2020).
cyst (continued). "Here, we demonstrate that hypoxia-inducible transcription factor (HIF) 1α upregulates MIF in cyst-lining cells in a tubule-specific PKD1 knockout mouse." (PMID 32885302, 2020). "In polycystin-1-deficient mice, recruitment and retention of renal macrophages were dependent on MIF, which promoted cyst expansion." (PMID 26858715, 2016). "Macrophage recruitment was associated with the upregulation of monocyte chemotactic protein 1 (MCP-1) and inflammatory cytokine TNF-α, which further induced MIF affecting renal epithelial cells and cyst development." (PMID 26858715, 2016). "In experimental murine polycystic kidney disease, MIF was required for renal inflammation and cyst expansion." (PMID 26441987, 2015). "MIF accumulated in cyst fluid of human ADPKD, promoted cystic epithelial cell proliferation and regulated apoptosis." (PMID 26441987, 2015). "Inducing exhaustion of macrophages or genetically deleting MIF demonstrated delayed cyst growth and improved renal function, supporting the notion that targeting macrophages and related factors could be a viable ADPKD treatment strategy." (PMID 41431718, 2026). "In particular, the MIF target genes in cell cycle regulation may provide another potential mechanism to support our finding that MIF is involved in the regulation of cystic renal epithelial cell proliferation, leading to cyst growth in kidneys." (PMID 38052787, 2023). "We previously reported that MIF promotes cyst growth in ADPKD." (PMID 36611841, 2022). "Functionally, MIF deletion or blockade can delay the cyst growth in ADPKD mice, indicating that MIF may involve in the pathogenesis of ADPKD." (PMID 35563296, 2022). "Cd74 could be activated using the macrophage migration inhibitory factor (MIF) to increase inflammatory cytokines in podocytes and tubular cells, along with proliferation in glomerular parietal epithelial cells and cyst cells." (PMID 33779731, 2021). "However, if cAMP-dependent upregulation of MIF can be referred to CREB in cyst epithelial cells has to be further analyzed in the future." (PMID 32885302, 2020). "In addition, in vivo MIF–mediated cyst growth has been referred to macrophage recruitment and the release of monocyte chemotactic protein 1 (MCP-1) and inflammatory cytokine TNF-α." (PMID 32885302, 2020). "• MIF is upregulated in cyst-lining cells in a polycystic kidney disease mouse model." (PMID 32885302, 2020). "Therefore, the exact role of MIF for apoptosis, and also potentially autophagy, and its contribution to cyst growth in ADPKD needs further investigation." (PMID 32885302, 2020). "However, the mechanisms leading to induction of MIF in renal epithelial and cyst-lining cells as well as its transport into the extracellular milieu have remained elusive so far." (PMID 32885302, 2020). "HIF-1α stabilization by the prolyl-hydroxylase inhibitor ICA did not only result in an increase of MIF protein in cyst-lining cells but also induced cyst growth which could be inhibited by the MIF-inhibitor ISO-1." (PMID 32885302, 2020). "• MIF is additionally regulated by cAMP, a strong promotor of cyst growth." (PMID 32885302, 2020). "Additionally, Nox4-deficient mice showed increased susceptibility to virulent RH strain infection and increased cyst burden in brain tissues and low levels of MIF expression following infection with the avirulent ME49 strain." (PMID 28743960, 2017). "By deleting MIF or by pharmacological inhibition, cyst growth was delayed in murine ADPKD models." (PMID 26858715, 2016). "Monocyte chemoattractant protein (MCP-1) and macrophage migration inhibitory factor (MIF) lead to an initial influx of pro-inflammatory macrophages, which then polarise towards a more anti-inflammatory, pro-proliferative activation state, driving cyst expansion and disease progression." (PMID 38283366, 2023). "Furthermore, MIF is also regulated by cAMP signaling to promote cyst growth in ADPKD." (PMID 35563296, 2022).